FPR2 (formyl peptide receptor 2)
Diseases named in the same sentence as FPR2 in open-access papers (continued):
Sharing a sentence is not in itself a finding about the gene and the disease.
endothelial dysfunction (4 papers, 2018 to 2022). In vascular diseases, endothelial dysfunction is a systemic pathological state of the endothelium (the inner lining of blood vessels) and can be broadly defined as an imbalance between vasodilating and vasoconstricting substances produced by (or acting on) the endothelium. "Further study is required to clarify the role of FPR2 of NK cell in the protection from or contribution to endothelial dysfunction in OSA." (PMID 31116781, 2019). "Thus, we speculate that chronic IHR may trigger NK cell migration through FPR2 activation, leading to endothelial dysfunction in patients with severe OSA." (PMID 31116781, 2019). "An amelioration of endothelial dysfunction, microflow recovery, and suppression of neutrophil infiltration was also shown, possibly involving the LXA4/FPR2/ERK1/2 pathway." (PMID 35956787, 2022). "On the other hand, paradoxical increase in FPR2 expression on NK cell was noted in a small subset of severe OSA patients, and correlated with endothelial dysfunction." (PMID 31116781, 2019). "Thus, our findings open the possibility of using synthetic FPR1 antagonists and FPR2/FPR3 agonists to resolve persistent inflammation and subsequent endothelial dysfunction in OSA." (PMID 31116781, 2019).
glioma (4 papers, 2008 to 2023). A benign or malignant brain and spinal cord tumor that arises from glial cells (astrocytes, oligodendrocytes, ependymal cells). "Our findings suggest that HN elicits a strong cytoprotective effect in GBM cells via the FPR2 membrane-bound receptor, facilitating tumor cell migration, angiogenesis and chemoresistance in glioma cells of heterogeneous genetic backgrounds." (PMID 37627089, 2023). "We found that FPR2 mediates the cytoprotective effects of HN in glioma cells." (PMID 37627089, 2023). "To evaluate the potential prognostic role of these markers in glioma, we stratified GBM patients according to the expression levels of HN or FPR2." (PMID 37627089, 2023).
Hyperglycemia (4 papers, 2017 to 2025). An increased concentration of glucose in the blood. "Hyperglycemia can decrease the levels of the pro-resolving lipid mediator RvD1 and downregulate RvD1 receptors, including FPR2." (PMID 40733247, 2025). "Here we shown that hrANXA1 protects the mitochondria from the detrimental effects of hyperglycemia in an FPR2-dependent manner." (PMID 30972066, 2019). "Furthermore, hyperglycemia enhanced the functional expression of a G protein coupled formylpeptide receptor 2 (FPR2)." (PMID 33212778, 2020). "Finally, the pathophysiological process of T2D may also be regulated by FPR2, which is upregulated in hyperglycemia." (PMID 40733247, 2025). "However, hyperglycemia-induced decreases in ALX/FPR2 were restored after Compound 49b treatment." (PMID 29095817, 2017).
injury (4 papers, 2016 to 2023). Damage inflicted on the body as the direct or indirect result of an external force, with or without disruption of structural continuity. "To confirm the possible functional significance of the rs11666254 polymorphism, we further investigated the association of this polymorphism with FPR2/ALX expression using ex vivo stimulation of whole blood with LPS in trauma patients." (PMID 28679406, 2017). "mtFPs activated FPR2 during the acute phase of IRI and mediated rat kidney injury by activating the migration and reactive oxygen species generation of neutrophils through the ERK1/2 pathway." (PMID 36658472, 2023).
lung fibrosis (4 papers, 2014 to 2024). "Taken together, SAA could induce a pulmonary fibrosis phenotype via FPR2, and CMTD had a significant protective effect against radiation- or SAA-induced lung injury." (PMID 39309438, 2024). "Inhibition of FPR2 significantly reduced pulmonary fibrosis induced by SAA administration in mice." (PMID 39309438, 2024). "And FPR2 inhibitor reduced Th-IR induced activation of the Rac1/NF-κB pathway in macrophages and further alleviated SAA-induced lung fibrosis." (PMID 39309438, 2024). "The expression of FPR2, an LXA4 receptor, increased during the development of IR-induced pulmonary fibrosis, whereas silencing of endogenous LXA4 using an antagonist (WRW4) or FPR2 siRNA resulted in impaired development of pulmonary fibrosis in response to IR." (PMID 32811815, 2020).
melanoma (4 papers, 2021 to 2023). A malignant, usually aggressive tumor composed of atypical, neoplastic melanocytes. "The antagonisms of FPR1 or FPR2 also inhibited the augmented invasiveness of melanoma cells co-cultured with neutrophils or incubated with NCM." (PMID 36766767, 2023). "Hence, we addressed this issue, showing AnxA1 secreted by neutrophils contributes to the development of melanoma lung metastasis by promoting cancer invasiveness through FPR1/FPR2 pathways." (PMID 36766767, 2023). "For this, murine melanoma B16F10 cells were applied, in which AnxA1 and its receptors (FPR1 and FPR2) were first characterized." (PMID 36766767, 2023). "Neutrophil co-culture enhanced the melanoma cell invasion, which was inhibited if melanoma cells were pre-treated with FPR1 and FPR2 antagonists." (PMID 36766767, 2023).
pancreatic cancer (4 papers, 2017 to 2025). "A study reported that LL-37 enhanced invasion, metastasis and tumorigenesis through FPR2 and P2X7 in pancreatic cancer stem cells." (PMID 36656313, 2023).
peritonitis (4 papers, 2015 to 2022). Inflammation of the peritoneum (tissue that lines the abdominal wall and covers most of the organs in the abdomen). "In this study, we evaluate the effects of the Fpr1 and Fpr2 agonists Ac9-12 and WKYMV, respectively, in carrageenan-induced acute peritonitis and LPS-stimulated macrophages." (PMID 35053343, 2022).
rheumatoid arthritis (4 papers, 2018 to 2025). A chronic, systemic autoimmune disorder characterized by inflammation in the synovial membranes and articular surfaces. "For instance, scolopendrasin IX from centipede venom exhibits dual antimicrobial and immunomodulatory properties, activating immune responses via formyl peptide receptor 2, thereby modulating inflammatory processes central to diseases such as rheumatoid arthritis." (PMID 40423312, 2025).
abdominal aortic aneurysm (3 papers, 2018 to 2025). Enlargement and ballooning of the vessel that supplies arterial blood to the abdomen, pelvis and legs. "FAM3D functions as a chemotactic agonist for the G protein-coupled receptors FPR1 and FPR2, strongly attracting immune cells such as neutrophils and monocytes, thereby contributing to the pathogenesis of abdominal aortic aneurysms." (PMID 41465269, 2025).
acute kidney injury (3 papers, 2020 to 2025). Sudden and sustained deterioration of the kidney function characterized by decreased glomerular filtration rate, increased serum creatinine or oliguria. "However, it is advisable that we also harness the wealth of past evidence that AnxA1 or its derivatives are useful when used to target FPR2/ALX to limit MI-mediated pathology and acute kidney injury." (PMID 33708206, 2021).
cystic fibrosis (3 papers, 2017 to 2023). Autosomal recessive disorder caused by pathogenic variants in the CFTR gene (cystic fibrosis transmembrane conductance regulator), which encodes a chloride and bicarbonate channel expressed in epithelial cells, and follow the diagnosis criteria. "The miR‐181b‐FPR2 axis was investigated further in airway epithelial and monocyte‐derived macrophage cells from cystic fibrosis patients, with evidence that miR‐181b is overexpressed whereas FPR2 is down‐regulated, in cystic fibrosis versus healthy cells." (PMID 35797341, 2022). "Anti‐miR‐181b strategies in these cells restored FPR2 expression, highlighting a potentially novel therapeutic target in cystic fibrosis." (PMID 35797341, 2022).
glomerulosclerosis (3 papers, 2024 to 2025). A hardening of the kidney glomerulus caused by scarring of the blood vessels. "A study demonstrated that MSC intervention prevented DN progression via the LXA4-ALX/FPR2 axis, which inhibited glomerulosclerosis and pro-inflammatory cytokines, eventually contributing to kidney homeostasis." (PMID 40862723, 2025). "By modulating the pro-inflammatory process via the lipoxin A4 LXA4-ALX/FPR2 axis, MSCs decrease the likelihood of DN progressing to glomerulosclerosis, inhibit glomerulosclerosis and pro-inflammatory cytokines, and contribute to kidney homeostasis." (PMID 39273032, 2024). "Notably, mesenchymal stem cells may inhibit glomerulosclerosis and pro-inflammatory cytokine release through the LXA4-ALX/FPR2 axis, thereby preventing the progression of DKD." (PMID 40443675, 2025).
inflammatory bowel disease (3 papers, 2017 to 2023). A spectrum of small and large bowel inflammatory diseases of unknown etiology. "Taken together, our study identifies FPR2 as a potential target for modulating LC3‐associated efferocytosis to alleviate intestinal inflammation and highlights the therapeutic value of COL, a natural and biased agonist of FPR2, in the treatment of inflammatory bowel disease." (PMID 37994307, 2023).
ischemia (3 papers, 2018 to 2023). A hypoperfusion of the BLOOD through an organ or tissue caused by a PATHOLOGIC CONSTRICTION or obstruction of its BLOOD VESSELS, or an absence of BLOOD CIRCULATION. "In contrast, immunohistochemical staining of neutrophils showed a significant decrease in neutrophil infiltration in ischemia–reperfused kidneys after FPR2 was specifically inhibited." (PMID 36658472, 2023).
neuroblastoma (3 papers, 2004 to 2022). Neuroblastoma (NB) is the most common solid, extracranial childhood tumor. "In addition, SPM receptors GPR32 and ALX/FPR2 were found to be expressed in differentiated neuroblastoma and microglial cells in this study." (PMID 35250536, 2022). "Interestingly, our study suggests that incubation of neuroblastoma cells with recombinant ANXA1 lead to an increase in NEP expression and this effect was reversed by FPR2 inhibitors." (PMID 27590054, 2016).
osteoarthritis (3 papers, 2013 to 2023). A noninflammatory degenerative joint disease occurring chiefly in older persons, characterized by degeneration of the articular cartilage, hypertrophy of bone at the margins and changes in the synovial membrane. "Compared with osteoarthritis (OA) synovia, elevated levels of 5- and 15-LOX, as well as ALX/FPR2, are detected in synovial tissue of RA patients." (PMID 27158677, 2016). "Higher levels of FPR2/ALX mRNA and LXA4 have been reported in the synovium and synovial fluid, respectively, of rheumatoid arthritis patients compared to osteoarthritis patients, suggesting a stronger involvement of the ligand-receptor system in inflammatory conditions." (PMID 24086560, 2013).
pneumococcal infection (3 papers, 2020 to 2024). Infections with bacteria of the species streptococcus pneumoniae. "We therefore compared WT, FPR1-, and FPR2-KO infected, either infected or uninfected, with or without Ac2-26 treatment 30 h after pneumococcal infection." (PMID 39768195, 2024).
pneumococcal pneumonia (3 papers, 2020 to 2022). A febrile disease caused by STREPTOCOCCUS PNEUMONIAE. "Similar findings were demonstrated in a murine model of pneumococcal pneumonia, in which Fpr2/3 KO mice also had shown exacerbated inflammatory response compared with their WT (C57BL/6) counterparts." (PMID 36078125, 2022). "In a recent study, it has been shown that Ac2-26 reduces the inflammatory response and bacterial loads after pneumococcal pneumonia and that this protective effect is mediated via FPR2." (PMID 33121515, 2020).
pneumonia (3 papers, 2021 to 2022). An acute, acute and chronic, or chronic inflammation focally or diffusely affecting the lung parenchyma, caused by an infection in one or both of the lungs (by bacteria, viruses, fungi, or mycoplasma.). "PSMs induce the necroptosis of neutrophils through the activation of mixed-spectrum kinase-like protein (MLKL) phosphorylation and increased release of lactate dehydrogenase, which mediates TNF-α secretion via formyl peptide receptor 2 (FPR2) and leads to the exacerbation of pneumonia." (PMID 35878202, 2022).
scleroderma (3 papers, 2019 to 2025). Scleroderma is a rare autoimmune connective tissue disorder characterized by abnormal hardening of the skin and, sometimes, other organs. "The therapeutic effects of WKYMVm in scleroderma-associated fibrosis and inflammation were completely abrogated in Fpr2 knockout mice." (PMID 31552041, 2019). "In this study, we showed that WKYMVm-induced activation of Fpr2 reduced the skin fibrosis which is associated with BLM-induced scleroderma." (PMID 31552041, 2019). "We have previously reported that activation of formyl peptide receptor 2 ameliorated dermal fibrosis by reducing the number of M2 macrophages in BLM-induced scleroderma." (PMID 33922418, 2021). "To explore the effect of Fpr2 activation in scleroderma, we established a scleroderma murine model by subcutaneous injection of bleomycin (BLM) for 3 weeks." (PMID 31552041, 2019). "We found that intradermal administration of WKYMVm, an Fpr2-specific agonist, alleviated bleomycin-induced scleroderma fibrosis in mice and decreased dermal thickness in scleroderma skin." (PMID 31552041, 2019). "Intradermal injection of WKYMVm decreased dermal thickness and collagen deposition in the scleroderma skin of wild type mice, whereas this therapeutic effect was completely abrogated in Fpr2 knockout mice." (PMID 31552041, 2019). "It has been shown that WKYMVm treatment increases the expression of Fpr2 in scleroderma fibroblasts and upregulation of Fpr2 in scleroderma fibroblasts fosters the switch to myofibroblasts." (PMID 31552041, 2019). "In the present study, we explored the effect of the Fpr2 agonist WKYMVm on fibrosis and inflammation in the scleroderma animal model, and clarified the role of Fpr2 in WKYMVm-induced therapeutic effect on scleroderma using Fpr2 knockout mice." (PMID 31552041, 2019). "In this study, we demonstrated that WKYMVm treatment reduced the number of CD68+CD163+ or CD68+Arginase-I+ M2 macrophages in the scleroderma tissues through Fpr2-dependent mechanism." (PMID 31552041, 2019). "In our study, WKYMVm treatment led to decreased production of myofibroblasts positive for α-SMA, Vimentin, and phospho-SMAD3 through an Fpr2-dependent mechanism in the scleroderma model." (PMID 31552041, 2019). "Finally, the indirect effect of FPR2 agonists on dermal fibroblasts has also been noted in settings of scleroderma." (PMID 40181186, 2025). "Furthermore, WKYMVm treatment did not reduce the numbers of Vimentin+ or Vimentin+p-SMAD3+ myofibroblasts in the scleroderma skin of Fpr2 KO mice, in contrast to the significant inhibition of those in the scleroderma skin of wild type mice." (PMID 31552041, 2019). "Moreover, WKYMVm treatment has been shown to promote differentiation of fibroblasts to myofibroblasts and matrix deposition in vitro, suggesting a deteriorating effect of Fpr2 activation in scleroderma." (PMID 31552041, 2019). "Moreover, WKYMVm treatment did not reduce the numbers of CD68+CD163+ or CD68+Arginase-I+ M2 macrophages in scleroderma skin of Fpr2 KO mice, in contrast to the WKYMVm-induced decrease of M2 macrophage levels in that of wild type mice." (PMID 31552041, 2019). "However, the role of Fpr2 in the progression of scleroderma remains elusive." (PMID 31552041, 2019). "However, WKYMVm treatment did not directly affect TGF-β1-induced differentiation of fibroblasts to α-SMA-positive myofibroblasts, suggesting that WKYMVm-induced activation of Fpr2 indirectly alleviates myofibroblast differentiation in the BLM-induced scleroderma model." (PMID 31552041, 2019). "However, the role of Fpr2 in the development and therapy of scleroderma is still unclear." (PMID 31552041, 2019). "To explore the role of Fpr2 in WKYMVm-induced alleviation of inflammatory responses in scleroderma mice, we next quantified the number of CD68-positive macrophages in Fpr2 knockout mice." (PMID 31552041, 2019).
scleroderma (continued). "To clarify the role of Fpr2 in WKYMVm-induced alleviation of scleroderma, we examined the therapeutic effects of WKYMVm on BLM-induced scleroderma in Fpr2 knockout mice." (PMID 31552041, 2019). "Taken together, these results suggest that WKYMVm-induced activation of Fpr2 alleviated BLM-induced dermal thickness, collagen deposition, and myofibroblast differentiation in scleroderma skin." (PMID 31552041, 2019). "Consistently, the increased level of hydroxyproline in the BLM-induced scleroderma skin was not affected by WKYMVm treatment in Fpr2 KO mice, in contrast to significant decrease of hydroxyproline content in the BLM-treated skin of wild type mice." (PMID 31552041, 2019). "The WKYMVm-induced reduction of TNF-α and INF-γ levels was observed in the serum of BLM-induced scleroderma model of wild type mice, but not in Fpr2 knockout mice." (PMID 31552041, 2019). "Moreover, WKYMVm treatment reduced the serum levels of inflammatory cytokines, such as tumor necrosis factor-α, and interferon-γ, in the scleroderma model of wild-type mice but not in Fpr2 knockout mice." (PMID 31552041, 2019). "In conclusion, the present study demonstrates that WKYMVm-induced Fpr2 activation relieves fibrosis by inhibiting fibroblast activation, macrophage infiltration and generation of M2 type macrophages, and inflammatory cytokine expression in BLM-induced scleroderma model." (PMID 31552041, 2019). "In contrast to the WKYMVm-induced decrease of fibrotic area in the scleroderma model of wild-type mice, WKYMVM treatment did not alleviate the BLM-induced dermal thickness in Fpr2 knockout mice." (PMID 31552041, 2019). "In contrast to the WKYMVm-induced inhibition of CD68-positive macrophage infiltration in the scleroderma skin of wild type mice, WKYMVm treatment had no significant impact on BLM-induced infiltration of macrophages in Fpr2 KO mice." (PMID 31552041, 2019).
alcoholic hepatitis (2 papers, 2020 to 2024). Acute hepatitis resulting from ingestion of alcohol. "Importantly, hepatic Fpr2 mRNA expression in alcoholic hepatitis was increased, contrary to receptors used by other SPMs such as resolvins." (PMID 32760397, 2020).
autoimmune disease (2 papers, 2020 to 2022). A disorder resulting from loss of function or tissue destruction of an organ or multiple organs, arising from humoral or cellular immune responses of the individual to their own tissue constituents. "Incomplete abrogation of LXA4 signaling due to a putative second receptor may explain why immunized global Fpr2-/- mice did not develop more severe autoimmune disease." (PMID 32118582, 2020).
Autoimmunity (2 papers, 2017 to 2024). The occurrence of an immune reaction against the organism's own cells or tissues. "Here, we aimed to elucidate the role of FPR2 in dendritic cell (DC) function and autoimmunity-related central nervous system (CNS) inflammation by using the experimental autoimmune encephalomyelitis (EAE) model." (PMID 39148732, 2024). "In conclusion, resolution initiated via activation of the ALX/FPR2 with AT-RvD1 has a significant impact in controlling tissue homeostasis, thus preventing acute inflammation from progressing to chronic autoimmunity." (PMID 28361884, 2017).
bacteremia (2 papers, 2012 to 2017). "This E. faecalis strain, an isolate from a bacteremia patient, showed an extraordinarily high level of FPR2/ALX activation." (PMID 22768166, 2012).
cognitive deficits (2 papers, 2020 to 2025). "Considering the data presented above, the involvement of FPR2 in RoI processes, cellular aging, and potentially in the modulation of cognitive deficits has been proposed, although the underlying mechanisms remain unclear." (PMID 40077816, 2025).
dermatitis (2 papers, 2025 to 2026). An inflammatory process affecting the skin. "Collectively, these results demonstrate that topical treatment of HA-Wm alleviates skin fibrosis and inflammation via an FPR2-dependent pathway, representing a promising noninvasive therapeutic avenue for fibrotic skin disorders such as systemic sclerosis." (PMID 41835787, 2026).